NES (nestin)
Diseases named in the same sentence as NES in open-access papers (continued):
Sharing a sentence is not in itself a finding about the gene and the disease.
tumor (continued). "In the recent years, the emerging concept of Nestin as a novel early angiogenic marker is gaining consensus in normal ad tumor angiogenesis." (PMID 25364727, 2014). "A right iliac crest bone marrow biopsy was performed, and it showed 60% infiltration with GFAP-positive and nestin-positive tumor cells, while synaptophysin was focally positive." (PMID 25563358, 2014). "Here, we aimed to gain insight into the use of Nestin as a marker for the origin of mural pericytes and SMCs in vascular stabilization processes during tumor progression." (PMID 25019063, 2014). "Our findings further confirm previous reports of a positive relationship between nestin expression and tumor malignancy." (PMID 24498263, 2014). "Nestin has been detected in various neoplasms such as astrocytomas and malignant gliomas, including glioblastoma multiforme and prostate cancer." (PMID 25505910, 2014). "We show here that blockade of VEGF by bevacizumab induces stabilization of angiogenic tumor blood vessels in human tumor specimen by recruiting Nestin-positive cells, whereas mature vessels down-regulated Nestin-expression." (PMID 25019063, 2014). "In our case, we found in bulge squamous area of neoplasia some nests of nestin-positive stroma cells with mesenchymal phenotype but also convincing clusters of nestin positive-cancer stem cells in the epithelial neoplasia." (PMID 24959179, 2014). "Our data demonstrate that nestin expression in NSCLC cells is associated with poor prognosis of patients and tumor cell proliferation pathway." (PMID 24498263, 2014). "A possible mechanism to account for the link between nestin expression and proliferation is proposed on the basis of results of our analysis of cell cycle regulation in tumor cells." (PMID 24498263, 2014). "This suggests that Nestin can be a marker of proliferating tumor endothelial cells and not only of neuroepithelial elements." (PMID 25364727, 2014). "Conversely, knockdown of nestin expression led to significant inhibition of tumor cell proliferation, decreased colony forming ability, and cell cycle G1 arrest." (PMID 24498263, 2014). "Tumor subsphere immunofluorescence assays also revealed that most Nestin-positive cells co-expressed Nanog, leading us to believe that the subspheres also contains undifferentiated neural stem cell." (PMID 24432012, 2014). "The expression of nestin protein between tumor cells and normal cells were also been showed using laser capture microdissection." (PMID 24498263, 2014). "Nestin knockdown in tumor cells resulted in prominent decrease in colony-forming ability (from 23% to 11.8% and 12.3% for shRNA1 and shRNA2 in A549 cells, and from 39.6% to 20.9% and 22.8% for shRNA1 and shRNA2 in A549 cells, respectively)." (PMID 24498263, 2014). "Nestin+/CD133+ cells within sections of human GBM are located in close proximity to tumor capillaries." (PMID 24868550, 2014). "Accordingly, we propose that promotion of Rb phosphorylation is one of the molecular mechanisms through which nestin induces tumor cell proliferation." (PMID 24498263, 2014). "The expression levels of Oct4 and Nestin were assayed in single tumor spheres to verify the self-renewal ability of cells within the spheres using immunofluorescence staining and confocal imaging." (PMID 25142304, 2014). "As a member of the class VI family of intermediate filament proteins and a cytoskeletal element, nestin has an effect in tumor cells similar to that of actin." (PMID 24966803, 2014). "Additional IHC analysis confirmed a significant increase of E-cadherin, EGFR and CD133 signals and reduced expression of Nestin protein in xenograft tumor samples belonging to PANC-1 shSMAD4 tumors as compared with the control group." (PMID 24625091, 2014). "Collectively, our findings demonstrate that nestin-expressing tumor cells are important for proliferation, apoptosis, migration, and metastasis in ESCC." (PMID 24966803, 2014).
tumor (continued). "Third-generation tumor spheres arising from GC1sp cells cultured under hypoxic conditions showed greater numbers of Oct4- and Nestin-expressing cells compared with that of the other three groups." (PMID 25142304, 2014). "To identify VM in primary human GBM sections, we used PAS and antibodies against CD34 and nestin to stain the tumor blood vessels." (PMID 23536763, 2013). "To identify normal stem cells present within the primary tumor or xenograft, we performed immunohistochemistry with antibodies specific for human or mouse nestin." (PMID 23527265, 2013). "Consistent with immunohistochemical staining, SOX2 and OCT4 were localized in the nucleus of tumor cells, Nanog was localized in the cytoplasm of cancer cells and Nestin was found to be present in the cytoplasm of endothelial cells, respectively." (PMID 23424657, 2013). "Our studies suggest that Oct4 and nestin expressing cancer cells are a different population of tumor-initiating cells." (PMID 24160469, 2013). "Human nestin was used as a marker for the presence of human tumor cells, as it is highly expressed in the tumor cells of our xenograft model." (PMID 24349039, 2013). "To verify that rat stromal cells outgrew EGFR amplified tumor cells from the three xenografts under different in vitro conditions, we used human- and rat-specific anti-nestin antibodies to detect and differentiate between cells from the different species." (PMID 24349039, 2013). "Since the nestin (+) and NeuN (+) cells were identified in two different regions of the tumor suggests that they are two separate cell populations." (PMID 24160469, 2013). "Widely used BTSC markers were in our hands not applicable: While we were unable to detect the CD133 antigen in paraffin embedded tissue sections, immunolabeling using an antibody directed to nestin resulted in widespread tumor cell immunoreactivity." (PMID 24086629, 2013). "We observed Nestin and Vimentin expression in the treatment groups as well as the controls, both in the tumor bulk and the invasion zone." (PMID 24312904, 2013). "The nestin (+) cells localized to the periphery of the tumor acini and the NeuN (+) cells were identified in the center of the acini." (PMID 24160469, 2013). "The level of nestin expression in tumour cells was found to be higher in primary tumours from patients with dissemination, when compared with patients without dissemination." (PMID 23998913, 2013). "In 48 cancer tissues, 32 cases (66.7%) showed Nestin positive-endothelium located frequently in the invasive front, and 6 csses in intra-tumor and 10 cases in both of them." (PMID 23424657, 2013). "Sel1L, regulates self-fate decisions and enhances tumor progression was expressed over 3 fold more in Oct4/GFP cells than the Nestin/GFP cells." (PMID 24160469, 2013). "Tumor initiation was slower in the U1752 cells taking 12 weeks for the Nestin/GFP cells to form a tumor." (PMID 24160469, 2013). "Serum free suspension culture exhibited a more variable cell composition in that the resultant cell populations were either predominantly nestin/SOX2 co-expressing rat stromal cells or human tumor cells, or a mixture of both." (PMID 24349039, 2013). "Most of the tumor cells were also immunopositive for nestin, a neural precursor/differentiation marker." (PMID 23922674, 2013). "In the EGFR-CD533 group, histology and nestin staining showed tumor cells with an epithelial-like phenotype compared to mesenchymal control cells." (PMID 23429996, 2013). "Most of these PDGF-induced tumours display characteristics of glioblastoma multiforme or of a primitive neuro-ectodermal tumour, and are nestin-positive, suggesting their derivation from an immature neuroglial progenitor." (PMID 23998913, 2013).
tumor (continued). "We have found Nestin expressed in both CD133-positive tumor cells and differentiated tumor cells, although the latter with down-regulation, which suggests the existence of residual neural stem cells after induced differentiation." (PMID 22995409, 2012). "Consistent with the previously reported study, BTICs derived from GBMs highly expressed nestin and Sox-2 compared to differentiated cultures derived from the same tumor tissues." (PMID 23110111, 2012). "Similar to the mouse xenograft models, rat nestin was expressed in tumor vessels and in glomeruloid microvascular proliferations in the biopsy xenografts." (PMID 22539956, 2012). "Staining for smooth muscle actin (SMA), which is a marker for blood vessel-associated pericytes, exhibited a similar pattern as that for host nestin, highlighting microvessels in the main tumor mass, as well as in the tumor invasive edge." (PMID 22539956, 2012). "Encapsulation of small tumor satellites by mouse nestin-positive cells was seen in satellites of sizes both smaller and larger than 100 μm, whereas infiltration by mouse nestin-positive cells was more pronounced in satellites that were >100 μm." (PMID 22539956, 2012). "We then compared adjacent tissue sections from tumor-bearing mouse brains stained for mouse nestin or GFAP." (PMID 22539956, 2012). "In the tumor border zone, where mouse nestin-positive cells accumulated, elongated bipolar cells expressed both nestin and GFAP." (PMID 22539956, 2012). "Human nestin expression was uniform and robust in the tumor cells both in low- and high generation lesions." (PMID 22539956, 2012). "In contrast, in low-generation xenografts, the tumor cells seamlessly infiltrated the brain, and we generally observed nestin-positive cells with an astrocytic morphology, comparable to what was seen at the site of mechanical injury." (PMID 22539956, 2012). "To distinguish between these possibilities we stained frozen tumor sections with nestin, MAP2, PDGFRβ, and β-catenin specific antibodies." (PMID 22891161, 2012). "Host nestin-positive cells appeared to originate in the subventricular zone (SVZ) ipsilateral to the tumor implant, and were present in the ipsilateral SVZ at some distance (1–3 mm) from the tumor mass." (PMID 22539956, 2012). "Mouse nestin-positive cells encapsulated and infiltrated small tumor satellites both in the ipsilateral and contralateral side." (PMID 22539956, 2012). "Rat nestin was similarly expressed in blood vessel walls in the immediate peritumor area and the tumor edge as well, although in these areas the microvessels assumed a normal (non-dilated) morphology." (PMID 22539956, 2012). "Mouse nestin-expressing cells were recruited to all three cell line xenografts, with a greater density of host cells observed at the tumor periphery in U251 xenografts." (PMID 22539956, 2012). "CD133-positive cells, isolated from the tumor, expressed stem cell markers including nestin, CD133, Ki67, Sox2, EFNB1, EFNB2, EFNB3, Cav-1, Musashi, Nucleostemin, Notch 2, Notch 4, and Pax6." (PMID 22995409, 2012). "CAF-1/p60, PARP-1 and nestin were expressed in all OSCCs; tumours were assigned to two (low-score and high-score) categories on the basis of the median values of marker expression." (PMID 22882088, 2012). "Given our observation that host nestin-positive cells contributed to the tumor neovasculature both in the mouse and in the rat xenograft models, we attempted to evaluate their spatial location in the vessels and mode of recruitment." (PMID 22539956, 2012). "Alcantara Llaguno and collaborators used a tamoxifen-inducible nestin−creERT2 transgene to deliver floxed tumor suppressors to the SVZ stem/precursor cells expressing nestin." (PMID 22973309, 2012). "In the tumor, cells with elongated morphology, as well as cells with astrocytic morphology stained positively for both rat nestin and GFAP." (PMID 22539956, 2012).
tumor (continued). "Along the invasive edge of the xenografts, we observed interdigitation of elongated, bipolar rat nestin-positive cells and tumor cells." (PMID 22539956, 2012). "At the tumor periphery, the majority of proliferating cells were tumor cells, whereas the brain parenchyma surrounding the tumor contained several host (mouse) nestin-positive cells that expressed PCNA, suggesting that these host cell were proliferating." (PMID 22539956, 2012). "This confirms xenograft data from other tumor types, where nestin positive cells in tumor vessels have been identified as endotheliocytes." (PMID 22539956, 2012). "Regions of tumor that appeared to be necrotic (depleted of DAPI stained cell nuclei) were surrounded by a halo of host nestin-positive cells, whereas the area lining the ventricle contralateral to the tumor had only few host nestin-positive cells." (PMID 22539956, 2012). "We focused on the three proteins (CAF-1/p60, PARP-1, and nestin) that showed the strongest correlation with each other and with tumour biological behaviour." (PMID 22882088, 2012). "The host nestin-expressing cells appeared to originate in the subventricular zone ipsilateral to the tumor, and were clearly distinguishable from pericytes that expressed smooth muscle actin." (PMID 22539956, 2012). "To confirm that our BTIC cultures derived from the surgically resected GBM tissues were indeed concentrated in tumor stem cells, we performed immunoblotting assays using antibodies directed against two well known stem cell markers, nestin and Sox-2." (PMID 23110111, 2012). "In both biopsies, only endothelial cells were immunopositive for nestin, a neural precursor/differentiation marker, whereas the tumor cells were immunonegative." (PMID 21494688, 2011). "Of interest, in addition to nestin the patient's recurrent tumor showed a propensity toward differentiation along neural lines, as demonstrated by increased expression of other neural markers such as CD56 or neural cell adhesion molecule and synaptophysin." (PMID 21494688, 2011). "The neural and endothelial precursor marker, nestin, was weakly expressed in the original (primary) tumor (0–1+)." (PMID 21494688, 2011). "This probably reflects a generalized expression of the nestin/IGF-I transgene that follows the spatial expression pattern of the nestin native gene throughout the tumor." (PMID 20214787, 2010). "Infection with a nestin promoter-directed oncolytc herpes virus prevented tumor formation, suggesting the tumor initiating cells were targetable by virotherapy." (PMID 19156211, 2009). "When analyzed at higher magnification, both LCMV-GP and VSV-G pseudotyped lentiviral vectors showed efficient transgene delivery to nestin-positive tumor cells in solid and invasive tumor areas." (PMID 19617915, 2009). "Since our previous work has shown that the xenografted tumours express nestin we stained the corresponding sections with a human-specific antibody against nestin to distinguish tumour cells from the surrounding host cells." (PMID 20040089, 2009). "The xenograft also expresses the neural progenitor marker nestin and closely recapitulates the histology of the patient tumor." (PMID 19617915, 2009). "To summarize, nestin-positive tumor cells were immunohistochemically detected in all of the examined osteosarcomas, although the proportion of Nes+ cells as well as the intensity of staining varied." (PMID 18925963, 2008). "Nestin-positive cells were rarely observed in 2 tumor samples, and the remaining 16 tumor samples showed various nestin expression patterns ranging from very sporadic occurrence to an overwhelming proportion of cells with strong positive staining." (PMID 18925963, 2008). "Over 90% of the cells in both SU-1 and SU-2 tumor spheres were nestin positive and about 5–10% stained positively for CD133." (PMID 18940013, 2008).
tumor (continued). "Although the nestin was detected in many kinds of solid tumors, its expression is widely recognized as a tumor marker especially of malignancies of neuroectodermal origin." (PMID 18925963, 2008). "We also successfully established permanent cell lines from the tumor tissue of 4 patients and immunodetection of nestin and CD133 was performed on these cell lines." (PMID 18925963, 2008). "The differentiation of most of the tumor cells seemed to be blocked at the progenitor cell phase: most of them expressed nestin but only a few co-expressed differentiation markers." (PMID 18940013, 2008). "At 16 weeks, there was significantly increased expression of mRNA for the stem cell marker Nestin in the tumor and immunohistochemical staining localized the increased expression to the basal layer of the epithelium." (PMID 17343742, 2007). "Following the immunodetection of nestin in ultrathin sections, a strong nestin positivity was observed throughout the cytoplasm of the tumor cells." (PMID 16457706, 2006). "Even though there have been several studies that focused on the detection of nestin in both tumor and normal cells, there are few publications describing the morphology of nestin cytoskeleton in individual human tumor cells." (PMID 16457706, 2006). "A thourough study of nestin in the nucleus of tumor cells on the ultrastructural level in combination with a precise molecular cytogenetic characterization of these cell lines will be a main aim of our future research." (PMID 16457706, 2006). "Collectively, all these findings suggest that nestin expression in tumor cells is closely related to their dedifferentiated status and increased malignancy." (PMID 16457706, 2006). "Furthermore, Wnt signaling can induce nestin expression by increasing β-catenin protein, leading to excessive proliferation or dedifferentiation of donor cells and promoting tumor formation." (PMID 40799240, 2025). "Targeting nestin can restore Gli3 function and inhibit tumor cell proliferation." (PMID 40799240, 2025). "Taking the results of the present study together with previous findings, a reevaluation of nestin’s role in tumor angiogenesis may be needed." (PMID 40149541, 2025). "Therefore, further research is needed to clarify the relationship between nestin expression and tumour behaviour, including its role in proliferation and progression." (PMID 39316249, 2025). "Therefore, it is feasible to use anti-tumor drugs targeting the signal pathway to target nestin for the treatment of MM in future research." (PMID 40799240, 2025). "Since Nestin expression is closely related to tumor malignancy, further studies on its regulation and functions may suggest new therapeutic targets that inhibit tumor growth and improve treatment outcomes in NSCLC and other cancers." (PMID 39941813, 2025). "An increased tumor volume in G4IDHwt was associated with the presence of immature cell populations (Nestin negative or weakly positive) (p = 0.018)." (PMID 40002588, 2025). "Besides, nestin expression was only found in a subset of the tumour cells that were identified on H&E." (PMID 40414994, 2025). "In addition, miR-204-5p has been found to directly target the 3'-UTR of Nestin mRNA, thereby continuously translating Nestin and inhibiting its expression to suppress tumor cell proliferation and promote apoptosis." (PMID 39944625, 2025). "For instance, a HSV-based oncolytic virus, CAN-3110 (formerly designated rQNestin34.5v.2), was engineered to express the viral gene, ICP34.5, to promote viral replication and oncolysis of the tumour cells specifically by placing the gene under the transcriptional control of a nestin promoter." (PMID 38615034, 2024). "The tumor biopsies of mice injected with P3 (PDX-P3) were very strongly positive for nestin." (PMID 38553638, 2024). "We reasoned that since Mary-X contains numerous tumor emboli nearly all within lymphatic spaces, that using the nestin reporter mouse could shed light on the nature of this process." (PMID 39669476, 2024).